AHR (aryl hydrocarbon receptor)
Diseases named in the same sentence as AHR in open-access papers (continued):
Sharing a sentence is not in itself a finding about the gene and the disease.
Cognitive impairment (22 papers, 2018 to 2026). Abnormal cognition is characterized by deficits in thinking, reasoning, or remembering. "In APP/PS1 transgenic mice, diosmin has caused the destruction of Aβ and improved cognitive impairment and memory deficit by activating the aryl hydrocarbon receptor (AhR) and increasing the expression of Neprilysin (NEP)." (PMID 40703750, 2025). "The impact of AhR deficiency on LPS-induced behavioral alterations were determined by assessing weight changes, cognitive impairment, and locomotor activity subsequent to systemic LPS injection." (PMID 41324080, 2025). "The present study first prompted that irisin could attenuate CKD-associated cognitive impairment through inhibiting AhR/NF-κB/NLRP3-mediated hippocampal neurons pyroptosis." (PMID 39698584, 2024). "The effect of uremic toxins was experimentally explored, and an increase in serum IS concentrations was shown to promote blood–brain barrier disruption associated with cognitive impairment by AhR activation in CKD rats established by an adenine-rich diet or by 5/6 nephrectomy." (PMID 38491448, 2024). "Recent evidence also suggests that inhibition of the AhR/NF-κB/JNK axis activates BDNF/TrkB signaling, which attenuates the progression of CKD and the cognitive deficits associated with CKD." (PMID 40791659, 2025). "In contrast, AhR activation is associated with a high-Trp diet, a NEP-dependent decrease in Aβ levels, and diminishing cognitive deficits in AD patients." (PMID 39335444, 2024). "Uremic toxin-activated AhR exerts detrimental biological effects on the development of CKD, CKD-associated cognitive impairment, anxiety, obstructive sleep apnea, ischemic myopathy and CVD, and DN." (PMID 38491448, 2024). "In transgenic model mice, AhR activation has been found to improve cognitive impairment and deficits by upregulating Aβ degradation." (PMID 39355779, 2024). "This cognitive impairment is associated with an increased permeability of blood-brain barrier (BBB) in rodents with CKD, linked to activation of aryl hydrocarbon receptor (AhR) by indoxyl sulphate (IS)." (PMID 39430169, 2024). "AhR signaling is implicated in age-related degenerative processes and CKD-related cognitive impairment." (PMID 39698584, 2024). "Reports indicate that indolepropionic acid, as an AhR agonist, can activate the immune system, reduce oxidative damage, inhibit lipid accumulation, and improve cognitive impairment." (PMID 39355779, 2024). "In the brain, indoxyl sulfate activates the aryl hydrocarbon receptor (AhR) on astrocytes and microglia, increasing oxidative stress and neuroinflammation and accelerating cognitive impairment." (PMID 38076538, 2023). "Activation of aryl hydrocarbon receptor by indoxyl sulfate also causes BBB disruption, which induces cognitive impairment in rodent models with CKD." (PMID 35959397, 2022). "Herein, both diosmin and I3C showed a significant therapeutic effect on cognitive deficits through AhR activation and NEP upregulated." (PMID 34522212, 2021). "The activation of AhR/NF-κB signaling could induce pyroptosis in hippocampus and contribute to CKD-associated cognition impairment." (PMID 39698584, 2024). "Indoxyl sulfate exposure in AhR knockout mice did not increase BBB permeability or cause any cognitive impairment indicating that the activation of AhR signaling disturbed the integrity of the BBB." (PMID 36757399, 2023). "Besides, similar cognitive impairment was observed after the specific deletion of AhR in neuroprogenitor cells." (PMID 30225360, 2018). "Regarding the relationship between NEP, AhR, and AD, it was demonstrated that AhR activation by Diosmin, Kyn, or I3C directly induces NEP expression, reducing Aβ levels and decreasing cognitive deficits in AD patients." (PMID 39335444, 2024). "Another study demonstrated that excessive AhR signalling activation of indigo sulphate in the blood elevated BBB permeability and induced cognitive impairment." (PMID 37445997, 2023).
Cognitive impairment (continued). "It is known that indoxyl sulfate can disrupt the integrity of BBB via the activation of AhR signaling in experimental CKD models of rats and mice and subsequently induce cognitive impairment." (PMID 36757399, 2023). "Another study demonstrated that excessive AhR activation of indigo sulphate in blood elevated BBB permeability and induced cognitive impairment." (PMID 37445997, 2023). "Some uremic toxins, such as indoxyl sulfate, has been reported to mediate the activation of the transcription factor aryl hydrocarbon receptor (AhR) to induce BBB disruption and uremia-related cognitive impairment." (PMID 36189322, 2022). "Studies on animals have found allelic differences in the aryl hydrocarbon receptor, which affect sensitivity to PCB exposure, resulting in cognitive deficits and motor dysfunction." (PMID 34589452, 2021). "Exposure to indole sulphate in AhR knockout mice did not result in increased BBB permeability or any cognitive impairment, suggesting that the activation of AhR signalling disrupted BBB integrity." (PMID 37445997, 2023). "The use of indole sulphate in AhR knockout mice did not result in increased BBB permeability or any cognitive impairment, suggesting that the activation of AhR signalling disrupts the integrity of the BBB." (PMID 37445997, 2023). "Recent experiments have highlighted that the direct toxicity of uremic toxins, such as the indoxyl sulfate-aryl hydrocarbon receptor pathway, may play an important role in BBB disruption and subsequent cognitive impairment in CKD." (PMID 35959397, 2022). "However, spatial learning remained unaffected, suggesting TCDD's specific influence on mood regulation rather than cognitive impairment, potentially through AhR activation." (PMID 39803412, 2025). "Furthermore, AhR activation has been found to downregulate the integrity of the blood–brain barrier (BBB), a factor thought to contribute to neurodegenerative pathologies such as cognitive impairment." (PMID 37445997, 2023).
leukemia (22 papers, 2012 to 2025). A malignant (clonal) hematologic disorder, involving hematopoietic stem cells and characterized by the presence of primitive or atypical myeloid or lymphoid cells in the bone marrow and the blood. "The findings in REH and Nalm-6 cells treated with KYN and IDO inhibitors confirmed the role of the AHR–IDO–KYN axis in leukemia cells." (PMID 35687267, 2023). "We analyzed AHR expression patterns in leukemia cell lines to explore the potential functional relationship among IP, AHR, and BCP-ALL." (PMID 35687267, 2023). "The proliferation and transformation of AHR-silenced leukemia cells were determined using BrdU incorporation and independent soft agar assays to further assess the tumorigenic effect of AHR on leukemia prognosis." (PMID 35687267, 2023). "It has been reported that AHR expression can be suppressed by promoter hypermethylation and subsequently inhibits Sp1 binding to the AHR promoter in human leukemia." (PMID 29212263, 2017). "The AHR agonist VAF347 also increased receptor levels in RA-treated HL-60 cells concomitantly with their differentiation to a granulocytic lineage; further supporting that AHR upregulation in leukemia cells favors a differentiated phenotype." (PMID 27243009, 2016). "Early studies have demonstrated a major role for the AhR in malignant B cell transformation including B lymphomas, leukaemia and multiple myeloma among other cancers." (PMID 25669983, 2015). "Additional evidence in HL-60 cells has supported the pro-differentiation role of AhR in leukemia." (PMID 37106727, 2023). "KYN levels were increased in leukemia cells treated with IP, thereby inducing AHR expression." (PMID 35687267, 2023). "The impairment of HIF-1α and AHR provided promising results against leukemia and myeloma." (PMID 34572746, 2021). "Altered AHR expression and activity have also been described in human leukemia and lymphoma cells." (PMID 27243009, 2016). "Furthermore, hypermethylation and repression of AHR gene were previously reported in various leukemia cell models." (PMID 27006469, 2016). "For example, benzene, an AhR agonist, is known to induce both leukemia and multiple myeloma." (PMID 23656719, 2013). "Interestingly, the AhR pathway is known to play a major role in the regulation of hematopoiesis, where altered AhR signaling can contribute to hematological disorders, including leukemia." (PMID 22754483, 2012). "Furthermore, AhR signaling induces a tolerogenic phenotype in dendritic cells (DCs), diminishing their antigen-presenting capabilities and production of pro-inflammatory cytokines, thereby impairing the initiation of effective anti-leukemia immune responses." (PMID 38539506, 2024). "In addition, AhR activation can induce the differentiation of naïve T cells into regulatory T cells (Tregs) and suppress the development of cytotoxic T lymphocytes (CTLs), which helps leukemia cells evade immune detection." (PMID 38539506, 2024). "Finally, AhR activation strengthens the immunosuppressive functions of myeloid-derived suppressor cells (MDSCs), frequently observed in the microenvironment of leukemic cells, further suppressing T cell responses and facilitating leukemia progression." (PMID 38539506, 2024). "Collectively, the activation of AhR by tryptophan catabolites plays a critical role in the TME to dampen immune responses, which contributes to immune evasion and leukemia progression." (PMID 38539506, 2024). "Further, to classify the regulation effect on leukemia patients, the expression level of AHR in patients with ALL was defined as the high group, in which AHR mRNA detected was sixfold higher than that in a normal donor." (PMID 35687267, 2023).
leukemia (continued). "We measured KYN expression and oncogenic activity in leukemia cells (REH and Nalm-6) to verify the regulatory effects of IP on AHR–IDO–KYN signaling." (PMID 35687267, 2023). "Analyses of eight leukemia cell lines (Nalm-6, Sup-B15, REH, Molt-4, K562, HL-60, Jurkat, and B-job) revealed higher AHR expression in B-cell leukemia cells (Nalm-6, REH, and Sup-B15) than in lymphoblastoid cell lines." (PMID 35687267, 2023). "Epidemiological studies have shown that exposure to environmental pollutants such as AhR agonists (TCDD) results in a significant increase in the incidence and pathogenesis of lymphoma and leukemia." (PMID 28103884, 2017). "Moreover, the up-regulation of genes involved in inhibition of apoptosis (e.g. MCL1) may promote the survival of leukemia cells with accumulated DNA damage and their expansion as suggested by an up-regulation of genes involved in cell cycle progression (AHR, AHR, TUBB2A, RAPGEF3, SERTAD1, FLT1)." (PMID 22848414, 2012). "In HL60 human leukemia cells, AHR levels increase during cell differentiation, with classic stem cell marker OCT4 expression decreased, indicating that positive regulation of AHR in leukemia cells could favor a cell differentiated phenotype." (PMID 35465323, 2022). "Tryptophan depletion and the consequent activation of the aryl hydrocarbon receptor (AhR) by kynurenine within the tumor microenvironment (TME) play a critical role in reshaping the interaction between immune and leukemic cells, thereby promoting immune surveillance and leukemia progression." (PMID 38539506, 2024).
bladder cancer (20 papers, 2014 to 2025). "The non-synonymous mutation Q383H has been detected in bladder cancer, and predicted as an activating mutation, and associated with higher AhR mRNA expression and activity." (PMID 38518996, 2024). "Amplifications of aryl hydrocarbon receptor (AHR) have been recently identified in bladder cancer, and its activation was also associated with grade, stage, and progression, confirming the protective role of its loss (100% of patients) observed in TGCA." (PMID 35841413, 2022). "A recent study identified a rare non-synonymous mutation (Q383H) in AHR as an APOBEC-associated hotspot mutation in bladder cancer, suggesting AHR as a potential driver of bladder cancer." (PMID 35710704, 2022). "Patients who harbor AhR-activating mutations may benefit from AhR-targeted therapies, although it is unknown why AhR somatic mutations are specific to bladder cancer." (PMID 38518996, 2024). "Interestingly, AhR somatic mutations have been specifically detected in samples from urinary tract cancer, primarily bladder cancer." (PMID 38518996, 2024). "However, the relevance and functional consequences of cancer-associated AHR mutations in bladder cancer are still poorly understood." (PMID 35710704, 2022). "On the other hand, the AhR agonist activity of coffee may also be exerting harmful effects, which could be exemplified by the controversial link between coffee consumption and bladder cancer, the risk of which has been shown to be increased in those occupationally exposed to PAHs." (PMID 25007155, 2014). "Collectively, this study demonstrates that P. distasonis‐derived 3‐IAA can inhibit bladder cancer metastasis and proliferation, highlighting the AhR‐FASN axis as a promising therapeutic target to inhibit bladder cancer progression." (PMID 40557796, 2025). "Based on current evidence, our study identifies a potential mechanistic link in bladder cancer by which a gut microbiota–derived metabolite induces ferroptotic cell death through the AhR‐FASN signaling pathway." (PMID 40557796, 2025). "To explore the relationship between the expression of AhR and the clinical features of bladder cancer, we analyzed data from the TCGA dataset to assess AhR expression across different clinical stages." (PMID 40557796, 2025). "Indole‐3‐acetic acid (3‐IAA) derived from gut P. distasonis binds to AhR in bladder cancer cells and downregulates FASN transcription, thereby increasing sensitivity to ferroptosis and suppressing the development of bladder tumors." (PMID 40557796, 2025). "Thus, activating mutations in AhR could be a driving event for bladder cancer." (PMID 38518996, 2024). "AHRQ383H leads to higher sensitivity of AhR to ligand activation, greater AhR activity, and increased dependency of luminal bladder cancer cells on AhR for cell survival." (PMID 38807762, 2024). "In contrast with HNSCC, which shows a AhR expression decrease with an increasing cancer grade, AhR expression was consistent across grade 1–3 cancers, whereas it increased in the stage 4 bladder cancer samples." (PMID 38680496, 2024). "Our data are also in line with previous ones demonstrating that in other tumors, TDO-derived Kyn activates AhR in an autocrine/paracrine manner to promote tumorigenesis of brain, breast, and bladder cancer cells." (PMID 35847038, 2022). "AhR binds to the promoter of both of these genes and is lower in bladder cancer, indicating a role of AhR in the protection of uroepithelial carcinomas." (PMID 27690298, 2017). "Further investigation is warranted to elucidate how AhR signaling regulates the expression or activity of FADS1 and FADS2 in bladder cancer, which may help uncover the mechanisms underlying the altered MUFA/PUFA ratio observed in our study." (PMID 40557796, 2025). "Our findings reveal a novel gut microbiota‐host interaction mechanism and suggest that the AhR‐FASN axis could serve as a therapeutic target in bladder cancer." (PMID 40557796, 2025).
bladder cancer (continued). "This discovery suggests that P. distasonis could be developed as a probiotic supplement for bladder cancer therapy by modulating the AhR‐FASN signaling axis." (PMID 40557796, 2025). "Moreover, knockdown of AhR reversed the inhibitory effects of 3‐IAA on bladder cancer both in vivo and in vitro, and similar results were observed upon treatment with an AhR inhibitor." (PMID 40557796, 2025). "AhR expression was high in bladder cancer cells, similar to the results obtained in HNSCC cells." (PMID 38680496, 2024). "The AhR expression levels in each immune cell type (macrophages, T cells, and Tregs) within the tumor nest were positively correlated with the stromal AhR expression in the corresponding cell type, which was comparable to that found in bladder cancer and HNSCC." (PMID 38680496, 2024). "AhR has both tumor-promoting and suppressive effects in bladder cancer." (PMID 38680496, 2024). "A broad suite of responses to fires in firefighters were identified that implicate urinary tract cancers, one carbon metabolism, xylene and PAH exposures, as well as signals that point towards a complex interplay between PAHs, AhR, indoles, and kidney and bladder cancer." (PMID 38012297, 2023). "The tendency of mutual exclusivity between AHR, FGFR3, and PIK3CA alterations may indicate convergence on the same pathway, although a fully independent parallel oncogenic pathway in bladder cancer driven by AHR cannot be excluded." (PMID 35710704, 2022). "Compounds such as such as 2,2’-aminophenyl indole (2AI), a potent synthetic agonist of AhR, may help to protect against bladder cancer by increasing UGT isozyme expression." (PMID 27690298, 2017). "Lastly, further research should be carried out to determine whether ligands acting on sex hormone receptors (AR or ER) and the GR isoforms or AhR targeting can provide preventive measures against bladder cancer as these are known modifiers of the UGT isozymes." (PMID 27690298, 2017). "Additionally, a recent study showed that AhR itself may suppress IFN-I expression in muscle invasive bladder cancer by directly interacting with and mediating the degradation of STING40." (PMID 38459088, 2024). "Taken together, these findings demonstrate that 3‐IAA binds to AhR and downregulates FASN transcription, thereby regulating ferroptosis in bladder cancer by disrupting the ratio of MUFAs to PUFAs." (PMID 40557796, 2025). "Mechanistically, 3‐IAA activates the aryl hydrocarbon receptor (AhR), which in turn downregulates fatty acid synthase (FASN) transcription in bladder cancer cells." (PMID 40557796, 2025). "In vitro experiments revealed that AhR knockdown attenuated the anti‐proliferative and anti‐clonogenic effects of 3‐IAA on bladder cancer cells." (PMID 40557796, 2025). "In addition, it was found that the recurrent in-frame deletions of exons 8 and 9 in the AhR gene displayed a high prevalence in bladder cancer comprising ~ 10 % of patients, which is highly specific to urinary tract cancer and mutually exclusive with other bladder cancer drivers." (PMID 38518996, 2024). "Compared with that in bladder cancer and HNSCC, the nuclear AhR expression in cancer cells was significantly higher than the cytosolic one." (PMID 38680496, 2024). "In addition, treatment with an AhR inhibitor (10 μM) largely reversed the anti‐proliferative and antimigratory effects mediated by 3‐IAA in bladder cancer cells." (PMID 40557796, 2025). "By investigating the role of amino acids in regulation of IFN-I production under chemo-drug treatment in bladder cancer (BC) cells, we find an inherent AhR-dependent negative feedback to restrain STING signaling and IFN-I production." (PMID 37670034, 2023). "SNPs in these gene regions (AHR and CYP1A1/2) have been identified in GWAS of blood pressure, bladder cancer and Parkinson's disease, although these may be explained by downstream effects of caffeine or coffee consumption or metabolism." (PMID 27741566, 2017).